MMP9 (matrix metallopeptidase 9)
Diseases named in the same sentence as MMP9 in open-access papers (continued):
Sharing a sentence is not in itself a finding about the gene and the disease.
hematoma (18 papers, 2014 to 2026). A hematoma is a collection of blood from a vascular structure into an extravascular space. "Hemoglobin released from hematoma lysis leads to iron deposition, glutamate deposition, free radical production, and antioxidase deactivation causing activation of matrix metalloproteinases-9 (MMP-9)." (PMID 27917153, 2016). "MMP-9 is not only involved in the breakdown of the BBB, but also in edema formation, hematoma enlargement, as well loss of neurons after hematoma." (PMID 35892330, 2022). "Results of main influencing factors PDGF-BB, VEGFA, Angpt1, MMP9, and GM-CSF were additionally confirmed by gene expression analysis, whereas except for GM-CSF all genes were expressed less in the smokers’ hematomas." (PMID 35621464, 2022). "Memantine, an FDA-approved NMDA antagonist for Alzheimer’s disease, showed benefit for ICH in animal studies with reduced hematoma growth, reduced inflammation with low MMP-9 level, less apoptosis, and better functional recovery." (PMID 27917153, 2016). "Compared with the MC group, the quantity of the perihematomal MMP-9 decreased after the hematoma was evacuated by the MI procedures." (PMID 24739149, 2014). "Some investigators have provided explicit evidence that the concentrations of MMP-2 and MMP-9 are significantly elevated in hematoma fluid, indicating that the MMP/VEGF system may be involved in the angiogenesis associated with CSDH." (PMID 35207175, 2022). "In contrast, we observed a reduced concentration of MMP-9 in the hematoma fluid." (PMID 35207175, 2022). "Furthermore, the knockdown of Nr4a1 significantly increased the expression of p-NF-κB p65, IL-1β, TNF-α, and MMP-9 with a decrease of ZO-1, occludin, and Lama5 in the peri-hematoma tissue." (PMID 31660977, 2019). "Pharmacological inhibition of JMJD3 by GSK-J4 attenuates neuroinflammation and subsequent BBB damage, accelerates hematoma resolution, and promotes histological and functional recovery after ICH, likely by downregulating MMP-9 expression." (PMID 42192766, 2026). "Our analysis indicated that VEGF, PDGF-BB, TNF-alpha, MMP-9, IL-6, CCL2, IL-1 alpha, MMP-1, MMP-8, and IL-8 were DEGs between the hematoma fluid and the peripheral blood before surgery." (PMID 35207175, 2022). "We found the evidence that NBP ameliorated neurological deficits, decreased hematoma expansion, brain water content, blood-brain barrier permeability and the expression of pro-inflammatory cytokine TNF-α and MMP-9 when dosed following ICH induction." (PMID 32564011, 2020). "We also examined the expression of MMP-9, a downstream of TNF-α in the peri-hematoma cortex tissue." (PMID 32564011, 2020). "Moreover, in comparison with the vehicle group, NBP group showed a lower expanded hematoma volume, brain water content, blood-brain barrier permeability, and TNF-α/ MMP-9 expression level." (PMID 32564011, 2020). "Besides, we performed ELISAs to evaluate the expression of MMP-9 and VEGF in the hematoma capsules." (PMID 34813498, 2021). "The increased baseline values for MMP-9 levels can be treated as a predictor of hemorrhagic transformation which occurs between the 5th and 7th day, whereas peak of MMP-9 at 24 h time point can be a predictor for the early (occurring within 48 h) parenchymal hematoma development." (PMID 31701356, 2020).
hyperlipidemia (18 papers, 2016 to 2025). "Additionally, MMP9 is considered a downstream mediator of inflammatory and matrix remodeling processes, which are functionally linked to lipid metabolism and hepatic injury in hyperlipidemia." (PMID 41304686, 2025). "The estrogen signaling pathway was regulated by CA binding to HSP90AA1, MMP2, RARA, PRKACA, ESR1, MMP9, and ESR2 in this present research, which underlies the improvements observed in hyperlipidemia and thrombosis." (PMID 38398534, 2024). "In our study, immunoblotting and IHC for MMP2 and MMP9 was used to investigate hyperlipidemia-induced fibrosis in renal tissue." (PMID 35845925, 2022). "MMP9 is secreted by vascular endothelial cells, smooth muscle cells, M lymphocytes, and T lymphocytes in hyperlipidemia-induced atherosclerotic plaques, and its overactivation leads to extracellular mesenchymal disruption, potential pathological remodeling, and restenosis." (PMID 38920980, 2024). "Our results directly attested that hyperlipidemia significantly inhibited the expression and the secretion of the MMP-9, NO, eNOS, and VEGF in myocardial tissue, which may account for that hyperlipidemia prevents EPCs mobilization stimulated by AMI." (PMID 36202115, 2022). "Our study showed that hyperlipidemia may attenuate the mobilization of BM EPCs induced by AMI via VEGF/eNOS/NO/MMP-9 signal pathway, which might partly account for hyperlipidemia hampering the repairs of AMI-induced cardiac injury." (PMID 36202115, 2022). "Circulating levels of MMP-2 and MMP-9 have been found to increase in patients with acute and chronic lower limb ischemia (i.e., intermittent claudication and critical ischemia), as well as in patients with hyperlipidemia when compared with healthy subjects." (PMID 31963569, 2020). "This remodeling could be mediated, at least in part, by MMP-9, as an HFD induced similar levels of hyperlipidemia in MMP-9-deficient mice, but there was no cerebrovascular remodeling." (PMID 34868060, 2021).
oesophageal cancer (18 papers, 1999 to 2023). "In situ gelatine gel profiles show that MMP2 and MMP9 gelatinolytic activity is enhanced in oesophageal squamous cell carcinoma and closely associated with vascular invasion in oesophageal cancer." (PMID 33995637, 2021). "LCN2, LOXL2, and MMP9 formed a ternary complex in oesophageal cancer cells, but the biological function of the ternary complex remained to be explored." (PMID 37753805, 2023). "The SRCR structure is a key domain through which LOXL2 interacts with both LCN2 and MMP9 to play an important biological role in oesophageal cancer." (PMID 37753805, 2023). "By activating both a non-specific tyrosine phosphatase inhibitor and a specific PTP1B inhibitor, it significantly reduces the secretion of MMP-2 and MMP-9 from leptin-stimulated oesophageal cancer cells, inhibiting cancer invasion through this mechanism." (PMID 37686525, 2023). "Our results showed that an LCN2/LOXL2/MMP9 ternary complex was formed in oesophageal cancer, with a distinctive intracellular and extracellular interaction pattern." (PMID 37753805, 2023). "Western blot analysis showed that the levels of MMP9 and vimentin in oesophageal cancer cells treated with apatinib and cytotoxic drugs were significantly decreased, and E‐cadherin expression was increased." (PMID 35315581, 2022). "In conclusion, we show that CD44 upregulation is associated with the loss of E-cadherin in esophageal carcinoma and that CD44 promotes MMP-9 mediated tumor invasion." (PMID 22069487, 2011). "There have been reports about the roles of MMP-9 expression in tumour invasion and metastasis, but this is controversial in oesophageal cancer." (PMID 14647147, 2003). "This suggested that the ternary complex of LCN2/LOXL2/MMP9 existed in oesophageal cancer cells." (PMID 37753805, 2023). "Therefore, the LCN2/LOXL2/MMP9 ternary complex can promote the invasion of oesophageal cancer cells by elevating the expression of MMPs to degrade gelatin and fibronectin." (PMID 37753805, 2023). "Moreover, both Transwell assays and invasion assays showed that overexpression of LCN2/LOXL2, LCN2/MMP9 and LOXL2/MMP9 enhanced the migration and invasion of oesophageal cancer cells." (PMID 37753805, 2023). "AP-1 increased MMP9 activity that increased esophageal carcinoma cells invasion and metastasis." (PMID 32856873, 2020). "To determine the appropriate treatment for superficial oesophageal carcinoma, we retrospectively studied expression of MMP-7 and MMP-9 and investigated clinical pathological factors and outcomes in superficial oesophageal cancer treated by endoscopic and surgical resection." (PMID 14647147, 2003). "The combined expression of MMP-7 and MMP-9 may be a good marker for the degree of malignancy of oesophageal cancer and for the presence of lymphatic metastasis." (PMID 14647147, 2003). "Although it had no relation with minute changes like lymphatic permeation, coexpression of MMP-7 and MMP-9 may suggest nodal metastasis in oesophageal cancer." (PMID 14647147, 2003). "This study was designed to determine whether VEGF, MMP-9 and E-cadherin expression is stable or changes in the process of lymph node metastasis of oesophageal cancer." (PMID 10424737, 1999). "Based on LCN2/LOXL2, LCN2/MMP9 and LOXL2/MMP9 protein–protein interactions, we further elucidated the molecular and cellular mechanisms underlying the LCN2/LOXL2/MMP9 ternary complex that promoted migration and invasion of oesophageal cancer cells, playing a synergistic role." (PMID 37753805, 2023). "The LCN2/LOXL2/MMP9 complex remodels the ECM and activates the FAK/AKT/GSK3β signalling pathway to enhance SPOCK1 expression, promoting the migration and invasion of oesophageal cancer cells." (PMID 37753805, 2023). "Non-cytotoxic DADS concentrations (<68 μM) block the invasion and migration of esophageal carcinoma cells OE19 by downregulating the expression of the MMP2 and MMP9 metalloprotease genes." (PMID 36559076, 2022).
oesophageal cancer (continued). "The oesophageal cancer cells treated with si‐HOTAIR or miR‐204 mimic exhibited decreased expression levels of HOXC8, Vimentin and MMP‐9, but increased E‐cadherin level." (PMID 31389660, 2019). "We showed that DFOM inhibited the migration and invasion of oesophageal cancer cells through multiple mechanisms, including reducing the expression of LCN2 and LLM, suppressing MMP9 enzyme activity, inhibiting cytoskeletal rearrangement, and thus restoring ECM remodelling." (PMID 37753805, 2023). "Therefore, LCN2/LOXL2/MMP9 activated the FAK/AKT/GSK3β signalling pathway to enhance SPOCK1 expression and remodel the ECM, thus promoting the migration and invasion of oesophageal cancer cells." (PMID 37753805, 2023). "Considering the crosstalk of functional roles of LCN2, MMP9 and LOXL2 in tumour progression, we hypothesized that an LCN2/LOXL2/MMP9 ternary complex might exist in oesophageal cancer and play a synergistic role in biological function." (PMID 37753805, 2023). "Also, in oesophageal cancer, it stimulates the release of MMP-2 and MMP-9, increasing the invasiveness of cancer cells." (PMID 37686525, 2023). "In conclusion, combined MMP-7 and MMP-9 expression may be a good marker for the malignancy level of oesophageal cancer and for the presence of lymphatic metastasis, not venous invasion." (PMID 14647147, 2003).
sarcoma (18 papers, 2011 to 2025). A usually aggressive malignant neoplasm of the soft tissue or bone. "More recently, Eom and Kim reported that a methanol extract from A. pilosa inhibits cell invasion by decreasing the levels and activities of MMP-2 and MMP-9 in HT1080 human sarcoma cells." (PMID 35337161, 2022). "In conclusion, our results show that cytokines and inhibitors regulate MMP-2 and MMP-9 expression in adult sarcoma cell lines, suggesting the clinical value of targeting these proteases for management of sarcomas and their pathogenesis." (PMID 24085323, 2013). "Additionally, in this study based on ELISA and gelatin zymography techniques, they observed that both MMP-2 and MMP-9 have reduced activity in the media from miR-182-deleted sarcoma cells." (PMID 36980984, 2023). "Hence, it appears that the increase of cell surface CD147 mediated by TRE17 enhances the signaling pathway, which induces the production of MMP1 and MMP9, resulting in increased invasiveness of HT-1080 sarcoma cells." (PMID 35926707, 2022). "Our results show that cytokines, mitogens, inducers and inhibitors have an up or down regulatory effect on MMP-2 and MMP-9 expression in adult sarcoma cell lines, suggesting these agents may be effective strategies to treat these cancers." (PMID 24085323, 2013). "Therefore, we chose three proteins such as BMP2, TGF-Beta, and MMP9 to confirm the expression levels using target proteomic analysis and Western blotting techniques using another newly recruited set of high-grade sarcoma patients (n = 18) of untreated and treated (n = 18) for confirmation analysis." (PMID 35806417, 2022). "Among all the tested sarcomas, 80.4% of the tumors were positive for COX-2, 90.2% were positive for MMP-9, and 100% were positive for PGP." (PMID 39061572, 2024). "In sarcoma, the expression levels of ANXA1 were positively correlated with those of MMP9 (r=0.204, P=9.43e-04), COL1A2 (r=0.349, p=8.87e-09), S100A4 (r=0.574, P<0.001), VIM (r=0.48, P<0.001) and S100A11 (r=0.638, P<0.001)." (PMID 36988561, 2023). "MSI was positively correlated with MMP-9 in COAD and sarcoma, whereas it was negatively correlated in four tumors." (PMID 35178444, 2022). "Both matrices are derived from Engelbreth-Holm-Swarm mouse sarcoma, and contain growth factors (EGF, FGF, TGFβ, IGF), ECM proteins (laminin, collagen IV, entactin), proteases (MMP-2, MMP-9), and perlecan." (PMID 30805306, 2019). "In our attempt to check a panel of suppressive molecules in the gene level, it was found more or less downregulation of Arginase 1, iNOS2, STAT3, IL-10, IDO, MMP9 and TGFβ in MDSCs from NLGP-treated surgically sarcoma removed mice." (PMID 28414726, 2017). "In this study, we compared MMP secretion patterns by cytokines, PMA and LPS in four adult sarcoma cell lines that express MMP-2 and MMP-9 to different extents." (PMID 24085323, 2013). "The highly aggressive pediatric sarcomas are characterized by high levels of matrix metalloproteinase (MMP)-2 and MMP-9, which play crucial roles in tumor invasion and metastasis by degradation of the extracellular membrane leading to cancer cell spread to distal organs." (PMID 24190483, 2014). "Of all the sarcomas (both FISS and non-FISS), 90.2% of the tumors were positive for MMP-9." (PMID 39061572, 2024).
type 1 diabetes (18 papers, 2008 to 2025). "In patients with type 1 diabetes, both acute hyperglycemia and hypoglycemia can cause surges in MMP-9, likely driven by oxidative stress." (PMID 41328144, 2025). "Type 1 diabetes: hyper/hypoglycemia spikes increase MMP‐9; GLP‐1 counterbalances these oxidative‐stress‐driven surges." (PMID 41328144, 2025). "The first aim of this study was to investigate plasma levels of FGF21, Cystatin C, lipocalin 2 and MMP-9 in children and adolescents with different duration of type 1 diabetes." (PMID 38932813, 2024). "A cross-sectional study showed associations of plasma levels of MMP9 and TIMP1 with PN in type 1 diabetes." (PMID 35651981, 2022). "We have recently shown that the levels of MMP-2 and MMP-9 were higher in serum from subjects with type 1 diabetes than in controls, whereas the levels of tissue inhibitors of metalloproteinases (TIMPs) were not affected." (PMID 22363890, 2011). "We further determined the concentrations of MMP-2 and MMP-9 in samples from subjects with type 1 diabetes and controls using ELISA." (PMID 19758433, 2009). "In a sub-group of patients with type 1 diabetes blood was drawn at time of and after diagnosis, with a mean time between samplings 1.3 ± 0.5 years (n = 42), the trajectory of circulating Cystatin C, MMP-9, lipocalin-2 and FGF21 was analysed." (PMID 38932813, 2024). "This study aimed to investigate plasma levels of FGF21, Cystatin C, lipocalin-2, and MMP-9 in children and adolescents with different duration of type 1 diabetes and possible correlation to HbA1c to identify potential biomarkers of future complication development." (PMID 38932813, 2024). "Thus, in type 1 diabetes model mice, the increase in AGEs promotes the secretion of MMP-9, destroying the basement membrane, increasing the loss of moisture through transpiration, and consequently, inducing skin dryness." (PMID 33390816, 2021). "Interestingly, IL-21 activity is increased in Helicobacter pylori infection, leading to higher production of matrix metalloproteinases MMP2 and MMP9, and MMP2 and MMP9 have been shown to be upregulated in Type 1 diabetes." (PMID 18773086, 2008). "Relationship by Pearson correlation coefficient (Pearson r) between MMP-9 and TIMP-1 in plasma and other laboratory data and neurophysiological tests in young adults with type 1 diabetes (n = 33)." (PMID 33775157, 2021). "Blood samples from patients with type 1 diabetes contained higher concentrations of MMP-2 and MMP-9 compared to healthy controls." (PMID 22363890, 2011). "The serum levels of both MMP-9 and MMP-2 were significantly higher in subjects with type 1 diabetes, compared to controls (p = 0.016 and p = 0.008 respectively)." (PMID 19758433, 2009). "In addition, increased circulatory MMP-9, as well as MMP-2, has been reported in older subjects with type 1 diabetes." (PMID 19758433, 2009).
bacterial meningitis (17 papers, 2009 to 2024). Inflammation of the membranes surrounding the brain and spinal cord due to a bacterial infection. "MMPs degrade the extracellular matrix and MMP8 and MMP9 are measurably increased in the CSF of patients with bacterial meningitis, with MMP9 associated with BBB dysfunction and neuronal apoptosis." (PMID 30423890, 2018). "A study of adults with TBM, viral, and bacterial meningitis found increased CSF MMP-9 concentrations were associated with more severe disease and death in all cases." (PMID 19789647, 2009). "MMP9 is a fairly well studied metalloproteinase, and increases in MMP9 have been shown in the CSF of patients with both viral and bacterial meningitis." (PMID 23185624, 2012). "Regarding bacterial meningitis, MMP-9 seems especially interesting, because its concentration increases in CSF and the brain tissue of patients and animals in an experimental setting." (PMID 20353584, 2010). "In previous studies, a positive correlation was shown between CSF TIMP-1 and MMP-9 in patients with bacterial meningitis; however, disease activity was higher in these patients and proteins were measured in CSF, which may explain the contradictory results." (PMID 36766708, 2023). "In humans, high levels of MMP-9 have been found in the CSF in both viral and bacterial meningitis." (PMID 30777092, 2019). "MMP-9 has been shown to induce BBB disruption and promote leukocyte extravasation in experimental bacterial meningitis and other models of neuroinflammation." (PMID 39080654, 2024). "ZmpC was identified as a critical facilitator in the development of bacterial meningitis, as evidenced by the detection of increased expression of TNF-α, IL-8, and matrix metalloprotease 9 (MMP-9)." (PMID 39080654, 2024). "We determined levels of MPO, MMP-8, MMP-9, and tissue inhibitor of metalloproteinase- (TIMP-) 1 in the CSF of children with bacterial meningitis and investigated how these inflammatory mediators relate to each other and to the disease outcomes." (PMID 31780869, 2019). "MMP9 knockout reduces neuro-inflammation in experimental autoimmune encephalomyelitis (EAE), while CSF MMP9 is elevated in patients with bacterial meningitis and BBB damage." (PMID 28086917, 2017). "Other authors assessed the CSF MMP-9 levels in patients with ALS as well as in subjects with inflammatory disease, such viral meningoencephalitis or bacterial meningitis." (PMID 25047909, 2014). "Similarly, elevated MMP-9 and the ratio of MMP-9 to tissue inhibitor of MMP-1 (TIMP-1) have been observed in the CSF of pediatric patients with bacterial meningitis, including tuberculous meningitis (TBM)." (PMID 35250814, 2022). "Mouse models of pyogenic bacterial meningitis demonstrate MMP-9∶TIMP-1 ratios are important predictors of tissue destruction, although MMP-9 may also have a significant role in host defense." (PMID 19789647, 2009).